APOE (apolipoprotein E)
Diseases named in the same sentence as APOE in open-access papers (continued):
Sharing a sentence is not in itself a finding about the gene and the disease.
dementia (continued). "In the A4 trial, older participants and those with higher levels of anxiety at baseline as measured by the STAI were more likely to discontinue while those who had a family history of dementia or were APOE ε4 carriers were less likely to drop out." (PMID 39044496, 2024). "In this study, we examined associations between established dementia risk factors (PTSD, TBI, and APOE ε4) and SCC, and the prognostic value of SCC in relationship to future EMR-determined ADRD diagnoses." (PMID 38951900, 2024). "As expected, dementia cases were older and had lower MMSE scores and fewer years of education but a higher prevalence of the APOE E4 allele and a larger proportion of females." (PMID 38365752, 2024). "When APOE genotype was added to the model, the effect of high HDL-C on dementia risk remained largely unchanged (HR 1.29, 95% CI 1.00, 1.67)." (PMID 38456089, 2024). "In fact, we observed that age, sex, APOE-ɛ4, and MMSE were independent predictors of time-to-dementia risk." (PMID 37605096, 2024). "Having a known family history of dementia (OR = 0.75 [95%CI = 0.55; 1.01]; p=0.063) and being an APOE ε4 carrier (OR = 0.79 [95%CI = 0.6; 1.04]; p=0.094) were marginally associated with study dropout." (PMID 39044496, 2024). "In subgroup analyses, the stronger protective effects of OA medications against dementia can be seen in older, late-onset dementia, male and APOE ε4 carrier subgroups." (PMID 39108220, 2024). "In individuals of African ancestry, 19q13.31:rs10423769-A was found to have a higher frequency in controls compared to both AD and related dementia cases among APOE ε4 homozygous or heterozygous carriers." (PMID 39606324, 2024). "Cases for both dementia outcomes were more likely to be women, older, more likely to be APOE-ɛ4 carriers, less physically active, less likely to be married, more likely to live alone, and had lower MMSE score." (PMID 37605096, 2024). "A variety of factors have been considered for their possible influence on IBA1 levels in the context of AD, including APOE and TREM2 risk variants, dementia, AD histopathology, and AD Braak staging." (PMID 39135132, 2024). "The observed associations were more pronounced in older, male, early-onset dementia, APOE ε4 carrier, OA duration >5 years, BMI ≥ 30 and TPA ≥ 3000 subgroups." (PMID 39108220, 2024). "Next, we further characterized these problem history subtypes according to the age of AD diagnosis, family history, APOE genotype, and co-occurrence of other types of dementia." (PMID 39649607, 2024). "When APOE ε4 carrier status was added in Model 2, the association between PRS and all-cause dementia lost statistical significance, but SCD remained a significant predictor." (PMID 39160600, 2024). "In conclusion, in a pooled analysis of dementia with Lewy bodies, Parkinson’s disease and Parkinson’s disease dementia, we have shown that APOE e4 is the major determinant of Lewy body diseases with dementia." (PMID 38978726, 2024). "Altogether, these studies suggest that the effect of APOE on NPS is possibly best captured before the dementia onset." (PMID 38279143, 2024). "Future research with larger samples should also examine the interaction between rate of conversion to dementia and APOE status in these groups." (PMID 38253819, 2024). "Understanding the distinct contributions of APOE isoforms is vital in identifying their impact on neurodegenerative disorders, particularly AD and related dementias." (PMID 38671950, 2024). "Another study found APOE to be an important moderator of progression to dementia among cognitively normal and MCI individuals with apathy domain." (PMID 38279143, 2024). "Other biological pathways linking AGEs and dementia in APOE ε4 carriers are, therefore, more plausible." (PMID 38218902, 2024). "A prospective cohort study showed us that carriers of FTO allele who were also carriers of apolipoprotein-E (APOE) ε4 allele have an increased risk of AD and dementia." (PMID 38255204, 2024).
dementia (continued). "In this large population‐based cohort of dementia‐free older adults, the concentration of blood biomarkers of AD varied in relation to multiple factors, including demographics, APOE genotype, medical conditions, and systemic inflammation." (PMID 38717935, 2024). "We investigated AD and dementia risks according to the presence of herpesvirus antibodies in relation to anti-herpesvirus treatment and potential APOE ɛ4 carriership interaction." (PMID 38306033, 2024). "MCI-AD and AD dementia patients were grouped by their APOE genotype into three age-similar categories: ε3ε3, ε3ε4, and ε4ε4." (PMID 38658964, 2024). "It is noteworthy that we confirmed previously reported determinants of dementia such as age, sex, APOE-ɛ4, MMSE, and physical inactivity." (PMID 37605096, 2024). "In agreement, Yu and colleagues conducted a randomized trial of 26 older adults who were APOE ε4 carriers with mild-to-moderate AD dementia." (PMID 39000060, 2024). "These APOE isoforms are of particular interest in AD and other dementias due to their critical roles in disease development and potential protective features." (PMID 38671950, 2024). "The Sydney multicenter study, the APOE longest cohort to date, reported an 83% incidence of dementia among patients surviving more than 20 years, underscoring the significant overlap between PD and dementia." (PMID 38356889, 2024). "Variants in ApoE, GBA, MAPT, α-synuclein (SNCA) have been proven to be associated with cognitive decline and dementia in PD." (PMID 38988604, 2024). "Strengths of our study include the large population in whom AGE levels, relevant other variables such as APOE ε4 and diabetes, and subsequent dementia incidence were assessed." (PMID 38218902, 2024). "Effect modification by APOE genotype has similarly been suggested for other demographic and vascular determinants of dementia." (PMID 38788076, 2024). "The results showed that the dementia progression in the Sleep+/APOE+ group was faster than in the Sleep+/APOE− and Sleep−/APOE+ groups, and significantly faster than in the Sleep−/APOE− group." (PMID 38421124, 2024). "Furthermore, unique cultural, social, and environmental characteristics of India, such as dietary practices and pathogen or toxicant exposures, may be associated with cognitive function and dementia and/or modulate the genetic effect of APOE ε4 in various ways." (PMID 38889280, 2024). "The ApoE−/− mouse model is a prominent dementia model characterized by significant amyloid-β plaque formation, neuroinflammation, and vascular dysfunction." (PMID 39583389, 2024). "There is increasing evidence that these factors interact with APOE ε4 on cognitive function and dementia." (PMID 38889280, 2024). "A previous study showed that in patients with DLB and Parkinsons's disease with dementia, younger age at diagnosis, female sex, lower MMSE, and apolipoprotein E (APOE) ε4 carriership were linked to excessive mortality relative to the general population." (PMID 39177108, 2024). "However, if APOE genotype is an important modifier of the effect, then studies involving human patients will need to account for APOE genotype to determine who is at risk for endotoxemia-induced dementia, and to plan for appropriate sample sizes for population-based studies." (PMID 38882697, 2024). "We investigated the effects of apolipoprotein E (APOE) ε4 and its interactions with sociodemographic characteristics on cognitive measures in South Asians from the Diagnostic Assessment of Dementia for the Longitudinal Aging Study of India (LASI‐DAD)." (PMID 38889280, 2024). "As it relates to dementia, TOMM40 is a well-established risk gene for late-onset AD and resides near APOE, and differential TOMM40 expression has been demonstrated in the brain." (PMID 39766777, 2024). "Our prospective cohort study also examined genetic influence, including APOE genotype and polygenic risk, on the association between dietary SPD, SPM and PUT intake and dementia risk." (PMID 39203912, 2024).
dementia (continued). "To do so, we conducted a retrospective cohort survival analysis using Cox regression models to evaluate the associations between PTSD, TBI, APOE ε4, and SCC on risk for dementia onset as determined in the medical record among Veterans aged 65 and older." (PMID 38951900, 2024). "Participants completed online surveys on health, demographics, modifiable dementia risk factors via a customized Dementia Risk Profile (DRP) tool and provided blood samples for APOE genotyping and plasma phosphorylated-tau (p-tau)." (PMID 39703924, 2024). "Specifically, we considered independent GWAS on any LBD, LBD stratified by APOE-ε4 status, PD, dementia in PD – representing a disease clustering with a strong APOE-ε4 contribution." (PMID 39415269, 2024). "Further studies on ApoE genotypes and ectopic pregnancy are needed to know if there are shared mechanism via ApoE between dementia and ectopic pregnancy." (PMID 39279812, 2024). "An interaction effect between APOE genotype and diabetes on cognitive function and dementia has previously been shown, though primarily between APOE ɛ4 and diabetes." (PMID 38926747, 2024). "Also, in males with one APOE e4, AA genotype might be linked to higher risk of dementia." (PMID 38863509, 2024). "The development of dementia is influenced by a variety of factors, including environmental factors (e.g., air pollution), genetics (e.g., apolipoprotein E gene), and comorbidities (e.g., hypertension or diabetes)." (PMID 38887243, 2024). "We also found that OA medications reduced the risk of dementia only in APOE ε4-positive participants, which provided new insights into dementia prevention among APOE ε4 carriers." (PMID 39108220, 2024). "Our research revealed a reduced incidence of MCI (OR = 0.745, 95% CI: 0.587–0.945, p = 0.015) and dementia (OR = 0.422, 95% CI: 0.259–0.688, p = 0.001) in the non-APOE ε4 carriers." (PMID 39639910, 2024). "Our study suggested that bilateral hippocampus was affected during the conversion from CN to dementia while only left hippocampus suffered significant affection with APOE ε4." (PMID 37323144, 2023). "A previous study showed APOE ε2 protective effects against clinical dementia in the oldest old (≥90 years), so this will be an exciting avenue for future work." (PMID 37459083, 2023). "The AD and mixed dementia groups had higher prevalence of APOE ɛ4 carriership than the controls, and APOE ɛ4 carriership was also more common in mixed dementia than in SSVD." (PMID 37980667, 2023). "The present study includes a large, racially diverse cohort with comprehensive demographic, behavioral, clinical, and APOE-ε4 genotype information and stringent ascertainment of dementia over a 32-year follow-up in the ARIC study." (PMID 36622673, 2023). "A previous study of our group showed that additive interactions combining NPSs (including depression) and APOE ε4 status emerged as consistent predictors of conversion to dementia in MCI." (PMID 36674881, 2023). "For our education and dementia example, APOE ε4 status has also been proposed as a modifier of the effect of low education on dementia." (PMID 38435670, 2023). "Multiple regression was used to assess the influence of CHIPS score and APOE carrier status on dementia severity based on Clinical Dementia Rating—Sum of Boxes (CDR-SB)." (PMID 36864910, 2023). "However, the role of APOE ε4 in the association between weight change and dementia risk is unknown." (PMID 35921193, 2023). "Analysis of MCI and dementia group cognitive outcomes by APOE ε4 status revealed that higher CSF ApoA1 levels in APOE ε4 carriers had a more rapid clinical progression." (PMID 36927447, 2023). "Our findings filled the gap in the mediation of APOE on brain atrophy and cognitive decline during the progression from normal cognition to dementia." (PMID 37323144, 2023).
dementia (continued). "Thus, whether socioeconomic status (education and income level), behavior (smoking status and leisure activities), and genetic factors (apolipoprotein E (APOE) allele status) modify the association between age at menopause and dementia is worth a further analysis." (PMID 37344154, 2023). "Fourth, we did not report the prevalence of CVD in the recruited subjects; future studies with information on the prevalence of CVD are warranted to better understand the association between APOE genotype, CVD, dementia and AD, especially in older men." (PMID 37680541, 2023). "One longitudinal study used ML to forecast dementia diagnosis in aMCI using sociodemographic, neuropsychological, and APOE variables as features." (PMID 38348371, 2023). "Conversely, lipid dysfunction, endothelial injury and vascular disease are risk factors for the development and progression of various types of dementia, including AD, where APOE ε4 carriage plays a major role." (PMID 36707869, 2023). "For instance, the Apolipoprotein E (APOE) transgenic mice (overexpressing human APOE3 or APOE4 gene), predisposed to developing AD and dementia, are shown to have decreased population of butyrate-producing gut microbiota." (PMID 37113148, 2023). "The secondary objective was to examine if baseline plasma ApoE level predicts cognitive function and incident dementia in a longitudinal and older cohort of GEM." (PMID 37666928, 2023). "ANOVA was used to test the effect of major dementia risk alleles in the TMEM106B and APOE genes on the hippocampal proteome and lipidome, adjusting for age, gender, and post-mortem interval." (PMID 36711721, 2023). "Of the APOE e4 carries with both low vitamin D and grip strength, 6.4% incident dementia compared to 2.4% of APOE e4 carries with both high vitamin D and grip strength." (PMID 37246226, 2023). "Clinical and genetic evidence clearly show that variants in ApoE and GBA1 are the highest risk factors for Lewy body dementia (LBD) and dementia onset in Parkinson’s disease (PD) patients." (PMID 37947642, 2023). "Within the APOE ε4 group, increased levels of CRP were associated with increased risk of AD and dementia." (PMID 37467176, 2023). "Previous studies investigated the effect of the APOE gene on retinal microvasculature in symptomatic AD and dementia; however, little is known about the effect of APOE on retinal microvasculature in the preclinical disease stage." (PMID 37685715, 2023). "al. similarly found APOE ε4 carriers show significant morphological deformation difference in both CN and dementia patients affecting the left hippocampus more than the right relative to noncarriers." (PMID 37323144, 2023). "Results of Cox regression of dementia diagnosis with sex, APOE ε4 status, cardiovascular problems at baseline, ethnicity and Townsend Deprivation Index (TDI) included in the model." (PMID 37467176, 2023). "PD patients carrying APOE ε4 have faster cognitive impairment and higher probability of progression to dementia." (PMID 37475029, 2023). "As for genetics, Apolipoprotein E (APOE) and polygenic scores are associated with a higher risk of AD, but the role of genetic factors in explaining future risk of dementia remains modest." (PMID 38031083, 2023). "Our findings filled the gap that APOE ε4 accelerates hippocampal atrophy and the conversion from normal cognition to dementia." (PMID 37323144, 2023). "Numerous groups have reported a significantly higher frequency of excess dementia and peripheral neuropathy in HIV-infected individuals carrying the APOE-ε4 allele, which is the strongest genetic risk factor for late-onset AD." (PMID 37496074, 2023). "Currently, some dementia-related genes (such as APOE, MPKA, and APP/PS1) have been found to have good clinical diagnostic value." (PMID 37189611, 2023).
dementia (continued). "In analyses in which APOE alleles were removed from the regression model, and the MCI group included AD and dementia cases, all AD PRS had strong association with MCI, with PRSsum having the strongest association (OR = 1.27,p-value = 1 × 10–15)." (PMID 37649099, 2023). "In FAD, the lifetime risk of dementia is very high, nearly 100%, while in SAD, the percentage is lower, about 22%–95% in APOE ε4-related AD and 7%–35% in APOE ε4-unrelated AD." (PMID 37589021, 2023). "Subsequently, a study demonstrated a significant association between APOE ε4 and EOAD which is modified by a family history of dementia." (PMID 37589021, 2023). "Several intensively studied dementia-affiliated genes such as APOE (apolipoprotein E), GBA1 (glucosylceramidase beta 1), LRRK2 (leucine rich repeat kinase 2), and PINK1 (PTEN induced kinase 1) encode proteins that function in the human metabolism." (PMID 36771351, 2023). "A higher frequency of APOE*44 in black compared to white and Asian participants is fund, but the effect estimates of APOE on incident dementia is much lower in black than in white." (PMID 37124771, 2023). "APOE ε4 genotype, age-related and dementia-specific brain pathology, among others, have been proposed as putative drivers." (PMID 37797059, 2023). "Although several studies have demonstrated an overrepresentation of APOE ε4 carriers among individuals with PD cognitive impairment and dementia, others have been equivocal or provided only modest evidence." (PMID 38026513, 2023). "Among dementia APOE ε4 carriers, higher CSF ApoA1 also had a faster rate of decline in MMSE (β − 1.03 [95% CI, − 1.95 to − 0.11], p = 0.029)." (PMID 36927447, 2023). "Walking pace was differently related to risks of new-onset dementia among participants with different APOE ε4 dosages (P for interaction = 0.001)." (PMID 36624486, 2023). "Genetic factors, notably familial Alzheimer's disease (FAD) and the apolipoprotein E (APOE) gene, are explored in detail, offering insights into their contributions to dementia susceptibility." (PMID 38074067, 2023). "Among dementia APOE ε4 carriers, higher plasma TG/HDL-C had a faster rate of decline in CDR-SB and higher plasma ApoA1 had a faster rate of decline in MMSE." (PMID 36927447, 2023). "ApoE and GBA1 are the most significant combined genetic risk factors for LBD and related dementias, and the in vivo experiments reported here tested functional and brain regional responses to GBA1 inhibition and loss of ApoE in mice models." (PMID 37947642, 2023). "There was a significant interaction between APOE ε4 and the association between PRS 1 and 2 for type 2 diabetes and all-cause dementia as well as between PRS 1–7 for type 2 diabetes and vascular dementia." (PMID 37091584, 2023). "Although all subjects were from a non-dementia population, APOE ε2 carriers still had higher MMSE scores in general cognitive situations, compared with APOE ε4 carriers (p < 0.001)." (PMID 37636817, 2023). "Although apolipoprotein E (APOE) genotype and educational attainment both influence dementia onset in sporadic AD, evidence for these effects in ADAD is limited." (PMID 37612284, 2023). "we inferred that (i) cognition function of APOE ε2 carriers is higher than APOE ε4 carriers in non-dementia older, especially in the memory cognitive domain." (PMID 37636817, 2023). "As such, our findings expand these previous studies by elucidating the value of GFAP for differential risk assessment of all-cause dementia and depression and by adding the information relating to SCC and APOE ε4." (PMID 37951931, 2023). "Our findings highlight the significance of APOE ε4 in accelerating hippocampal atrophy and the conversion process from CN to Dementia." (PMID 37323144, 2023).